CSPG4P11 (chondroitin sulfate proteoglycan 4 pseudogene 11)
Gene: Transcribed unprocessed pseudogene on chromosome 15 (84,186,752 to 84,197,384, forward strand). Ensembl gene ENSG00000259726.
Diseases named in the same sentence as CSPG4P11 in open-access papers:
CSPG4P11 is named in the same sentence as 1 disease in open-access papers, as found by Europe PMC text mining. Sharing a sentence is not in itself a finding about the gene and the disease. The quoted sentences say what the papers report.
schizophrenia (1 paper, 2018). A major psychotic disorder characterized by abnormalities in the perception or expression of reality. "In addition to CSPG4P11, which showed a significant SMR association with schizophrenia in the present study, these included CD46, encoding the CD46 complement regulatory protein, GOLGA2P7, encoding GOLGA2 pseudogene 2, and SLCO4C1, encoding Solute Carrier Organic Anion Transporter Family Member 4C1." (PMID 30419947, 2018).